RNU6-449P (RNA, U6 small nuclear 449, pseudogene)
Gene: Small nuclear RNA gene on chromosome 15 (53,764,204 to 53,764,310, forward strand). Ensembl gene ENSG00000206641.
Homologues: Orthologues: chimpanzee U6 (98% identical), macaque U6 (93% identical), pig U6 (70% identical). Paralogues in human: RNU6-797P (85% identical), RNU6-1145P (84% identical), RNU6-188P (84% identical), RNU6-38P (84% identical), RNU6-742P (84% identical), RNU6-74P (84% identical), RNU6-83P (84% identical), RNU6-1316P (83% identical), RNU6-409P (83% identical), RNU6-480P (83% identical), RNU6-698P (83% identical), RNU6-1089P (82% identical), and 1285 more.